Y_RNA (Y RNA )
Gene: Miscellaneous RNA gene on chromosome 11 (40,351,564 to 40,351,672, forward strand). Ensembl gene ENSG00000206806.
Homologues: Orthologues: chimpanzee Y_RNA (98% identical), zebrafish Y_RNA (63% identical). Paralogues in human: RNY1 (82% identical), Y_RNA (81% identical), Y_RNA (80% identical), Y_RNA (79% identical), RNY1P8 (78% identical), Y_RNA (78% identical), RNY1P11 (77% identical), Y_RNA (77% identical), Y_RNA (76% identical), RNY1P10 (75% identical), Y_RNA (75% identical), RNY1P5 (74% identical), and 90 more.